RNU4-77P (RNA, U4 small nuclear 77, pseudogene)
Gene: Small nuclear RNA gene on chromosome 1 (233,448,626 to 233,448,781, reverse strand). Ensembl gene ENSG00000252501.
Homologues: Orthologues: chimpanzee U4 (87% identical), macaque U4 (80% identical), dog U4 (52% identical), pig U4 (43% identical), mouse Gm26425 (40% identical), rat LOC120102560 (40% identical), mouse Gm22956 (37% identical), mouse Gm55605 (36% identical), guinea pig U4 (35% identical). Paralogues in human: RNU4-41P (54% identical), RNU4-16P (53% identical), RNU4-67P (53% identical), RNU4-84P (53% identical), RNU4-42P (53% identical), RNU4-44P (53% identical), RNU4-13P (52% identical), RNU4-20P (51% identical), RNU4-23P (51% identical), RNU4-56P (51% identical), RNU4-7P (51% identical), RNU4-48P (51% identical), and 81 more.